PBRM1 (polybromo 1)
Diseases named in the same sentence as PBRM1 in open-access papers (continued):
Sharing a sentence is not in itself a finding about the gene and the disease.
renal carcinoma (continued). "The role of PBRM1 in the systemic therapy of renal cancer is unknown." (PMID 35368029, 2022). "Thus, PBRM1 might be a promising predictor for the targeted therapy of renal cancer and the predictive role of PBRM1 in targeted therapies of renal cancer needs to be further studied." (PMID 35368029, 2022). "Moreover, inactivation of PBRM1/BAF180 reduced IFNγ-STAT1 activity in renal carcinoma." (PMID 34865122, 2021). "Notably, the high incidence of mutations in PBRM1 in renal cancer seems to be limited to clear cell histology and mutations are rare or not observed in other renal cancer subtypes, such as papillary (4%) or chromophobe (0%)." (PMID 31861590, 2019). "We also collected the renal cancer tissue that was assessed for the expression of classical onco‐suppressor genes, downregulated in RCC, namely von Hippel–Lindau (VHL) Polybromo‐1 (PBRM1), SETD2, and BAP1." (PMID 39806854, 2025). "Therefore, we hypothesized that UBE3A might promote PBRM1 degradation in renal cancer cells." (PMID 35368029, 2022). "Together, these findings demonstrate that UBE3A interacts with PBRM1 and UBE3A silencing increases the PBRM1 protein levels in renal cancer cells." (PMID 35368029, 2022). "Thus, our results indicate that PBRM1 is a bonafide substrate of UBE3A and is involved in proteasomal degradation in renal cancer cells." (PMID 35368029, 2022). "In addition, we checked the clinical relevance of PBRM1 and UBE3A in a tissue microarray of patients with renal cancer." (PMID 35368029, 2022). "The subsequent coimmunoprecipitation experiment verified that PBRM1 and UBE3A could bind to each other in 293T and renal cancer cell lines (786-O and ACHN cells)." (PMID 35368029, 2022). "Our results agree with a previous work that demonstrated that PBRM1 expression is a negative prognostic factor in renal carcinoma." (PMID 31212728, 2019). "Therefore, to ensure that the methylation changes seen across renal cancers were not due to the confounding effect of VHL and other mutations, we selected a group of pan-negative WT samples by excluding samples with VHL, BAP1, or PBRM1 mutations." (PMID 37528416, 2023).
breast carcinoma (27 papers, 2012 to 2025). "Gene copy number variation (CNV) analysis of SETD2, BAP1, PARP-3 and PBRM1 within a panel of nine breast cancer cell lines demonstrated single copy number loss of all candidate genes within five (56%) cell lines (including 21NT cells)." (PMID 28977912, 2017). "This is particularly interesting given a recently documented role for PBRM1 loss in renal and breast cancers." (PMID 23082233, 2012). "Low expression of PBRM1 in breast cancer tissues is associated with an unfavorable outcome." (PMID 41278204, 2025). "PBRM1 binds to the p21 promoter and regulates baseline and signal-dependent p21 transcription, thereby inhibiting tumor development in breast cancer cells, indicating that PBRM1 is a tumor suppressor gene mutated in breast cancer." (PMID 38365747, 2024). "In addition, MDA‐MB‐231 breast cancer cells (PBRM1 I228V missense mutation) were also used to rescue PBRM1 expression and to validate the functions of PBRM1 and obtained similar results." (PMID 36178086, 2022). "In breast cancer, PBRM1 is necessary for p21 expression, regulating cell cycle arrest, and functioning as a tumor suppressor." (PMID 39541575, 2025). "PBRM1 alterations are also observed in several other cancers, including non-small cell lung cancer, cholangiocarcinoma, and breast cancer at lower levels than ccRCC." (PMID 39541575, 2025). "In conclusion, our findings demonstrated that exosomal SNHG12 regulates HUVEC angiogenesis to promote breast cancer progression by interacting with PBRM1 to target MMP10." (PMID 38833118, 2024). "The SV40-immortalised breast cell line MTSV and the HCC1143 breast carcinoma cell line were found to have undergone distinct copy number alterations within the PBRM1 locus compared with the other loci examined." (PMID 28977912, 2017). "Several studies identified PBRM1 as a prognostic indicator in breast cancer patients." (PMID 41278204, 2025). "PBRM1 is a tumor suppressor gene that binds to the p21 promoter and upregulates its baseline and signal-dependent transcription, subsequently inhibiting tumor development in breast cancer cells." (PMID 41278204, 2025). "PBRM1 expression is strongly correlated with clinical stage and lymph node status and serves as a significant indicator for overall survival and recurrence-free survival in breast cancer patients." (PMID 41278204, 2025). "Similarly, breast cancer cDNA array analysis revealed a significant inclusion pattern of PBRM1 E27 in cancer tissues compared with that in normal tissues." (PMID 39375538, 2024). "As a tumor suppressor gene, PBRM1 may be involved in the occurrence and development of breast cancer and is a valuable prognostic indicator for breast cancer patients, further research is needed to explore other potential molecular mechanisms." (PMID 38365747, 2024). "PBRM1 is an essential factor that independently impacts the prognosis of breast cancer patients." (PMID 38365747, 2024). "Due to the high frequency of gene copy number loss within breast cancer cells, our results provide additional evidence that SETD2, BAP1, PBRM1 and PARP-3 may function as tumour suppressors in breast cancer cells." (PMID 28977912, 2017). "In breast cancer, PBRM1 is shown to be a core regulator of p21; however, we could not find a similar pattern in ccRCC." (PMID 27556922, 2016).
breast carcinoma (continued). "Compared to matched non-cancerous tissues, the expression of PBRM1 is significantly decreased in breast cancer tissues, and its low expression is associated with poor clinical outcomes in breast cancer patients, further indicating its tumor suppressor function." (PMID 38365747, 2024). "Similar to the BAF subfamily, the mutations in auxiliary subunits in the PBAF subfamily, such as PBRM1 and ARID2, are frequently observed in breast cancers." (PMID 41278204, 2025). "We demonstrated that SNHG12 was highly expressed in both breast cancer cells and their secreted exosomes, promoting HUVEC angiogenesis and tumor progression via PBRM1 and MMP10." (PMID 38833118, 2024). "We next performed real-time qPCR on the breast cancer cell lines and normal breast tissues using primer sequences specific to the candidate genes SETD2, BAP1 PBRM1 and PARP-3 (Figure 2Ci-2Civ)." (PMID 28977912, 2017). "Furthermore, we identified additional breast cancer genes deleted more frequently in warm/hot tumors than in cold tumors (BAP1, PBRM1, NOTCH1, CCND1, RB1)." (PMID 38714665, 2024). "Both PBRM1 and TCF21 have been shown to have tumor suppressor-like functions in breast cancer." (PMID 31430859, 2019). "In the present study, overexpression of BAP1, but not PARP3, PBRM1 or SETD2, was associated with significant (but not complete) repression of hTERT transcription within 21NT breast cancer cells." (PMID 28977912, 2017). "In order to investigate the functional role of SETD2, BAP1, PBRM1 and PARP-3 in regulating hTERT transcription, we examined the effect of forced, stable overexpression of candidate genes on pre-spliced hTERT expression within 21NT breast cancer cells." (PMID 28977912, 2017). "In addition, we have demonstrated that SETD2, BAP1, PBRM1 and PARP-3 are all down-regulated in the breast cancer cell line 21NT when compared to normal cells (HMEC), making them prime targets for tumour suppression / telomerase repression in breast cancer." (PMID 28977912, 2017).
kidney cancer (25 papers, 2014 to 2026). Primary or metastatic malignant neoplasm involving the kidney. "Among the top 10 mutated genes found in the kidney cancer dataset, PBRM1, BAP1, SETD2, and VHL have been implicated in tumor progression and poor prognoses." (PMID 39199616, 2024). "As reported in kidney cancer, patients with PBRM1‐truncating mutations had significantly longer overall survival (OS) than those with PBRM1 non‐truncating mutations but not non‐synonymous mutations." (PMID 37649319, 2023). "Above all, ccRCC (e.g., Caki-1 cells) is accounted for in kidney-cancer-related deaths and is mutated in the von Hippel–Lindau (~90%), PBRM1 (~50%), and BAP1 (~15%) genes." (PMID 37628997, 2023). "Recently, variations in VHL and PBRM1 mutation rates were observed according to ancestry, with fewer mutations in African kidney cancer patients." (PMID 33668731, 2021). "Similarly, in kidney cancer, the tumor suppressor PBRM1 binds H3K14ac via its bromodomains, and mutations disrupting this interaction alter gene expression and compromise tumor suppression." (PMID 41283357, 2025). "Fdcyd is also currently under assessment in clinical trials of various advanced solid tumors, suggesting the finding might have translational utility in kidney cancer types which PBRM1 is mutated." (PMID 35719970, 2022). "PBRM1, the second most highly mutated tumor suppressor gene in kidney cancer, encodes PBRM1." (PMID 31863007, 2019). "Regarding somatic mutations, VHL has the highest prevalence (43.2%) in the entire population considered from the kidney cancer TCGA dataset (N = 424), followed by PBRM1 and MUC4, both slightly above 20%." (PMID 39199616, 2024). "Afterwards, we analyzed the gene mutations in the high-risk and low-risk groups of the advanced kidney cancer and discovered the mutation of some genes, such as VHL, CHEK2, BAP1, PBRM1, which were closely related to RCC." (PMID 35739510, 2022). "According to the TCGA report, the most frequent gene mutations in kidney cancer were VHL, PBRM1, SETD2, and BAP1." (PMID 35055428, 2022). "We also find that expressions of PBRM1 and p21 correlate with each other in human kidney cancer samples." (PMID 31863007, 2019). "Together with HIF1α, it promotes glycolysis of kidney cancer cells, and the researchers also observed that PBRM1 deficiency can promote the proliferation, migration and invasion of 786-O and SN12C cells, and high levels of PB1 can prolong the life expectancy of kidney cancer patients." (PMID 39609317, 2024). "Polybromo‐1 (PBRM1) is an important tumor suppressor in kidney cancer." (PMID 30585695, 2019). "Since p21 is a CDK inhibitor and its activation leads to G1/S cell cycle arrest, we analyzed whether reduced p21 induction after DNA damage in PBRM1-depleted cells affected cell cycle progression in kidney cancer cells." (PMID 31863007, 2019). "Previous studies have found that several genes, including VHL, PBRM1 and TSC1, played an important role in tumorigenesis of kidney cancer." (PMID 34193180, 2021).
kidney cancer (continued). "While a single knockout of Vhl and Pbrm1 failed to develop kidney cancer in mice, both Bap1-Vhl and Bap1-Pbrm1 double-knockout mice developed ccRCC." (PMID 40688406, 2025).
melanoma (22 papers, 2013 to 2025). A malignant, usually aggressive tumor composed of atypical, neoplastic melanocytes. "Expression of interferon γ inducible genes, including chemokines that recruit effector T cells, increased in PBRM1-depleted mouse melanoma cells and this was associated with increased chromatin accessibility at regulatory sites." (PMID 35323214, 2022). "A CRISPR-Cas9 screen analysis found that ARID2, BRD7, and PBRM1, components of the PBAF complex, sensitized mouse melanoma cells to T-cell cytotoxicity, and PBRM1-deficient murine melanomas were found to be infiltrated by more cytotoxic T cells." (PMID 36361605, 2022). "In human cancers, expression of Arid2, and Pbrm1 is related to expression of T-cell cytotoxicity genes, which confirmed in Pbrm1-deficient murine melanomas with strongly infiltrated by cytotoxic T cells and responsive to immunotherapy." (PMID 32850400, 2020). "In human cancers, expression of Arid2 and Pbrm1 are related to expression of T cell cytotoxicity genes, which confirmed in Pbrm1-deficient murine melanomas with strongly infiltrated by cytotoxic T cells and responsive to immunotherapy." (PMID 32864131, 2020). "It was reported that Pbrm1-deficient murine B16F10 melanomas were more immunogenic and more responsive to immunotherapy." (PMID 32358509, 2020). "In addition to modulation of melanoma sensitivity to immunotherapy, a study suggests that loss of PBRM1 confers synthetic lethality to inhibitors of DNA repair." (PMID 35323214, 2022). "However, Dr. Wucherpfennig's group found that IFN α/γ responsive genes were significantly up-regulated in ARID2 and PBRM1-deficient B16F10 melanoma cells, leading to enhanced T cell infiltration and regression of murine melanoma." (PMID 34865122, 2021). "Conversely, a Cas9-screen based approach in melanoma cells previously implicated PBRM1 loss enhanced cytokine expression, a more immunogenic TME and greater response to ICB24, and similarly we found that other tumor lineages did exhibit immunostimulatory effects following PBRM1 loss." (PMID 32358509, 2020). "Though we found a consistently decreased immunogenic TME in ccRCC patients with PBRM1 loss across 5 patient cohorts, a previous Cas9-based screen in murine melanoma cells indicated that loss of PBRM1 may increase tumor immunogenicity." (PMID 32358509, 2020). "Similarly PBRM1 was found to be infrequently silenced by mutations in human cancer cell lines; in contrast, PBRM1 has been found to be silenced in 3.6–7% of stomach, endometrial, melanoma, pancreatic, cervical, bladder, and head/neck cancers based on the TCGA database." (PMID 25774356, 2014). "Molecular profiling confirmed the diagnosis of melanoma and identified mutations in the TERT promoter, NRAS, NF1, PBRM1, FAT1, and ATM genes." (PMID 40125165, 2025). "PBRM1 and BRD7, which are mutated at lower frequency in melanoma than ARID2, were also identified in an unbiased CRISPR/CAS9 screen as modulators of resistance to T cell-mediated killing and sensitivity to immunotherapy." (PMID 35323214, 2022). "We first looked at an extended list of high-risk genes predisposing to melanoma (ACD, CDKN2A, CDK4, POT1, TERF2IP, and TERT) or RCC (CDKN2B, FH, FLCN, MET, PBRM1, PTEN, SDHs, TSCs, and VHL) or both (BAP1 and MITF)." (PMID 34067022, 2021). "To test whether this has clinical potential, we created two PBRM1 KO clones in the mouse melanoma B16-F10 cell line for in vivo studies." (PMID 40011561, 2025). "Therefore, there are multiple therapeutic opportunities for exploiting PBRM1 disruptions in melanoma." (PMID 35323214, 2022). "PBRM1 is a PBAF subunit that has six tandem bromodomains and the gene is most frequently mutated in renal clear cell carcinoma and at lower frequencies in other cancers, including melanoma." (PMID 35323214, 2022).
melanoma (continued). "Consistent with the TCGA analysis, PBRM1 mutations were most common in ccRCC patients (46.6%), followed by non-melanoma skin cancer (9%) and melanoma (8%), while ARID2 was most common in melanoma (13%), followed by non-melanoma skin cancer and colorectal cancer (11%)." (PMID 32820162, 2020). "Still, it is not clear why ARID2 is so frequently mutated in melanoma compared to other SWI/SNF subunits, including other components of PBAF like PBRM1." (PMID 35323214, 2022). "Although not as frequently mutated in melanoma as ARID2 and SMARCA4, PBRM1 protein levels are highly sensitive to the levels of SMARCA4 protein and incorporation into the SWI/SNF complex requires the presence of ARID2." (PMID 35323214, 2022). "In a large number of human tumors, expression of PBRM1 is negatively correlated with the expression of T-cell cytotoxicity genes and murine melanomas lacking Pbrm1 are more likely to be infiltrated by cytotoxic T cells." (PMID 34671561, 2021). "Inactivation of three genes, including polybromo 1 (PBRM1), AT-rich interaction domain 2 (ARID2), and bromodomain containing 7 (BRD7), that code for PBAF, one of the chromatin-remodeling complexes of the SWI/SNF, sensitized melanoma cells for destruction by T cells." (PMID 34827646, 2021).